HES1 (hes family bHLH transcription factor 1)
Diseases named in the same sentence as HES1 in open-access papers (continued):
Sharing a sentence is not in itself a finding about the gene and the disease.
colorectal cancer (27 papers, 2015 to 2026). A primary or metastatic malignant neoplasm that affects the colon or rectum. "Downregulation of Notch/Hes1 signaling was associated with Notch-regulated dendritic cell immune responses (IRs) in a mouse colitis colorectal cancer model." (PMID 37728427, 2023). "Abnormalities in KRAS-mediated differentiation and proliferation were linked to activation of the HES-1 transcription factor in colorectal carcinomas." (PMID 32974155, 2020). "Regarding the interaction between Hes1 and metastasis, patients presented high Hes1 still had an increased risk of death from colorectal cancer." (PMID 26650241, 2015). "We further explored the expression of Hes1 in human colorectal cancer and found high Hes1 mRNA expression is associated with poor prognosis in CRC patients." (PMID 26650241, 2015). "Since high Notch expression is observed in colorectal cancer and is associated with the tumor stage, we were interested in knowing whether Hes1 is involved in the tumorigenesis of colon adenocarcinoma." (PMID 26650241, 2015). "For example, in colorectal cancer, inhibiting key genes of the Hes1 and Wnt pathways (such as CTNNB1, CCND1) can affect tumor cell proliferation and apoptosis." (PMID 40755759, 2025). "The precise role of HES1, a canonical Notch downstream transcription repressor, in intestinal carcinogenesis is controversial, with studies differing on the relationship between HES1 and colorectal cancer (CRC) outcomes." (PMID 37749297, 2023). "HES1 has been shown to promote cell invasion via STAT3-MMP14 pathway and is associated with poor prognosis in colorectal cancer." (PMID 37046345, 2023). "On the contrary, our group found that nuclear HES1 expression is lost in 91% of sessile serrated adenomas/polyps (SSA/p) and most of the right-sided colorectal cancer which commonly harbors BRAF or KRAS mutation." (PMID 37749297, 2023). "In colorectal cancer, HES1 facilitated the aggressive progression via activating Bim1 transcription and repressing PTEN transcription." (PMID 33390847, 2021). "FAM83H-AS1, Notch1 and Hes1 were significantly increased in colorectal cancer samples and cell lines." (PMID 32839509, 2020). "Molecules in the Notch signaling pathways, including HES1, Notch-1, and Jagged-1, are highly expressed in colorectal cancer stem cells." (PMID 31198409, 2019). "Transcriptional repressor Kruppel-like factor (KLF4) inhibits the abnormally differentiated cells in colorectal cancer and HES-1, a downstream molecule of Notch-1, can inhibit the expression of KLF4." (PMID 31198409, 2019). "Notch-1, Jagged-1 and Jagged-2 (two of the 5 Notch ligands), and its target gene Hes-1 are expressed in human primary adenocarcinomas and colorectal cancer cell lines." (PMID 30323897, 2018). "Weng MT found that HES1 controls invasiveness via the STAT3-MMP14 pathway in colorectal cancer (CRC) cells." (PMID 29665790, 2018). "Genes of Notch signaling pathway such as Notch1, Notch2, HES1, DLL1, and JAG1 have been reported to be associated with the pathological tumor characteristics and degree of differentiation in colorectal cancer." (PMID 29100272, 2017). "In colorectal cancer, where elevated HES1 expression is correlated with distal metastasis and poor prognosis, this protein enables upregulation of EMT markers like vimentin and N-cadherin, thereby promoting the invasive ability of cancer cells." (PMID 28122586, 2017). "According to the multivariate Cox regression analyses, Hes1 (HR, 2.41; 95% CI, 1.07 to 5.43) and MMP14 (HR, 2.36; 95% CI, 1.02 to 5.46) remained positively associated with deaths from colorectal cancer." (PMID 26650241, 2015). "In the present study, we explored the expression of Hes1 in human colorectal cancer and correlated its expression with the clinical results." (PMID 26650241, 2015).
colorectal cancer (continued). "While HES1 expression is normal in benign hyperplastic polyps and normal colon tissue, HES1 expression is often lost in sessile serrated adenomas/polyps (SSAs/SSPs) and colorectal cancers (CRCs) such as those right-sided CRCs that commonly harbor BRAF or KRAS mutations." (PMID 36824959, 2023). "Moreover, NOTCH/HES1 axis inhibition accompanied by PPARγ activation can repress the progression of colorectal cancer via suppressing cancer stem cells." (PMID 36147468, 2022). "However, colorectal cancer patients with co-morbid type 2 diabetes have abnormal cellular proliferation, which was correlated with increased Notch1/HES1 signaling and curbed by metformin treatment." (PMID 36672573, 2022). "In contrast to our results, some studies have demonstrated that increased HES-1 expression may be an adverse prognostic factor in colorectal cancer." (PMID 32974155, 2020). "In this study, we explored the role of Hes1 in the tumorigenesis of colorectal cancer." (PMID 26650241, 2015). "To date, there has been scant data about Hes1 expression in colorectal cancer." (PMID 26650241, 2015). "The co-expression of Hes1 and ARID3B is associated with poor prognosis in colorectal cancer, and they may synergistically recruit histone-modifying enzymes (such as KDM4C) to regulate chromatin structure, thereby activating PD-L1 immune checkpoint transcription and inhibiting T cell activity." (PMID 40755759, 2025). "Prior studies suggested that HES-1 might play an oncogenic role in colorectal cancer." (PMID 32974155, 2020). "Unlike oxaliplatin, these complexes do not enhance the expression of HES-1, a crucial gene in the Notch signaling pathway implicated in colorectal cancer self-renewal and tumorigenicity, suggesting they may disrupt the signaling mechanisms supporting cancer stemness." (PMID 40733139, 2025). "In colorectal cancer RKO and HCT8 cells, Hes1 overexpression upregulates ABC transporters (ABCC1, ABCC2, P-gp), reducing intracellular drug uptake/accumulation and inducing 5-Fu chemoresistance." (PMID 40755759, 2025). "Blocking the Notch1/Hes1 axis enhances radiosensitivity by suppressing proliferation, exacerbating radiation-induced DNA damage (e.g., DSBs), and impairing DSB repair in colorectal cancer." (PMID 40755759, 2025). "In colorectal cancer (CRC) cell lines, RIP140 positively regulated HES1 gene expression at the transcriptional level via a recombining binding protein suppressor of hairless (RBPJ)/neurogenic locus notch homolog protein 1 (NICD)‐mediated mechanism." (PMID 38459621, 2024). "Hes1 expression depletion is often observed in sessile serrated adenomas/polyps (SSA/p) and colorectal cancer." (PMID 37728427, 2023). "HES-1 has been proposed as harboring oncogenic activity in colorectal cancer but has not been investigated in adenocarcinoma of the small intestine, where the drivers of oncogenesis are not as well-understood." (PMID 32974155, 2020). "Up-regulation of ZNF671 in colorectal carcinoma (CRC) cells resulted in suppressive effects on proliferative ability and metastatic potency via the deactivation of Notch signaling, with decreases in expression of Notch1, NICD, HES1 and HEY1." (PMID 39595048, 2024). "Nevertheless, studies in relation with HES1 expression in CRC are controversial suggesting that it is not a good marker of NOTCH signaling activation in colorectal cancer." (PMID 30380753, 2018).
osteosarcoma (26 papers, 2009 to 2026). A usually aggressive malignant bone-forming mesenchymal neoplasm, predominantly affecting adolescents and young adults. "Additional evidence from osteosarcoma xenografts in mice has shown the transcriptional repressor Hairy and Enhancer of Split 1 (HES1) to be associated with tumour dormancy and a more repressive chromatin state." (PMID 37608096, 2023). "The high expression of Hes1 in patients with osteosarcoma is usually associated with a poor survival rate." (PMID 36975516, 2023). "It was reported that expression of Hes1 was associated with invasive and metastatic potential in osteosarcoma." (PMID 26452029, 2015). "It was reported that expression of Hes1 was associated with invasive and metastatic in osteosarcoma cells." (PMID 26452029, 2015). "HES1 expression has been associated with increased aggressiveness in human osteosarcoma cell lines." (PMID 40563676, 2025). "Furthermore, this study also showed that 61 dogs with primary osteosarcoma who underwent amputation and standard chemotherapy revealed that overexpression of Hes1 in tumor tissues was significantly associated with increased disease-free survival." (PMID 36975516, 2023). "Moreover, the metastatic and invasive potential of osteosarcoma cells is associated with Hes-1 expression." (PMID 34671398, 2021). "Notch signaling and HES1 expression have been linked to growth and survival in a variety of human cancer types and have been associated with increased metastasis and invasiveness in human osteosarcoma cell lines." (PMID 23816051, 2013). "HES1 expression was also found to be variable between cell lines in canine and human osteosarcoma cells." (PMID 40563676, 2025). "Studies have shown that the increased expression of miRNA-216b can regulate the JMJD2C/HIF1α/HES1 signaling axis in osteosarcoma cells, thereby increasing cisplatin-induced apoptosis and effectively treating osteosarcoma." (PMID 39857292, 2025). "Human Deltex (DTX1) was also shown to regulate NOTCH1/HES1 signaling negatively in osteosarcoma cells." (PMID 38900140, 2024). "A study found that the transcription of NOTCH1.Jag1 and target genes (Hes1 and Hey2) was upregulated in osteosarcoma specimens." (PMID 36975516, 2023). "The results indicate that NOTCH signal activation plays an important role in the advancement of canine osteosarcoma through the overexpression of Hes1." (PMID 36975516, 2023). "A study found that the expressions of NOTCH1, NOTCH2, Hes1, and Hey1 increased markedly in primary canine osteosarcoma." (PMID 36975516, 2023). "Blocking the NOTCH signaling pathway inhibits the occurrence and development of primary tibial tumors by downregulating Hes1 in orthotopic xenograft osteosarcoma mouse models." (PMID 36975516, 2023). "As showing in the results, we found that silencing CEMIP significantly decreased the protein expression of Notch receptor Notch1, Notch ligand Jagged1, and Notch target gene Hes1 in osteosarcoma cells." (PMID 35957875, 2022). "In conclusion, their results demonstrated that curcumin exerts an inhibitory effect on osteosarcoma cell proliferation and invasion by inhibition of Notch-1 signaling, following the suppression of Hes-1, cyclin D1, MMP-2, and MMP-9 expression." (PMID 34671398, 2021). "Studies revealed that Notch pathway genes including Notch1, Notch2, Notch ligand DLL1, and Notch target genes including Hes-1, Hey-1, and Hey-2 were expressed in osteosarcoma cells." (PMID 34671398, 2021). "HES1 promotes invasiveness and metastasis in vivo; therefore, an over-expression of HES1 and under-expression of Deltex1 are seen in osteosarcoma conditions." (PMID 34769401, 2021). "In contrast, sample from the recurrent osteosarcoma were insensitive (inhibition rate: 0.00%) to cisplatin treatment with low Notch1 and HES1 expression." (PMID 24894297, 2014).
osteosarcoma (continued). "In our study, we for the first time identified that the expression of Notch1 and HES1 in osteosarcoma specimens were positively correlated with cisplatin sensitivity in osteosarcoma patients." (PMID 24894297, 2014). "Messenger RNA levels of HES1 were measured in canine and human osteosarcoma cell lines and confirmed using Western blot analysis using a rabbit monoclonal anti-human HES1 antibody as described to determine if HES1 mRNA levels correlated to protein expression." (PMID 23816051, 2013). "Immunohistochemical examination revealed that HES1 was accumulated in the nuclei of human osteosarcoma samples." (PMID 19455146, 2009). "A study found that NOTCH3 could also promote the invasion and metastasis of osteosarcoma cells by upregulating the downstream target genes Hes1 and MMP7." (PMID 36975516, 2023). "According to Zhang and colleagues, HES1 can directly downregulate Dtx1, which is acting as a negative regulator of Notch1 signaling, through degradation of the intracellular domain of Notch1 in osteosarcoma." (PMID 28122586, 2017). "Interestingly, sample from the primary osteosarcoma were sensitive to cisplatin treatment (inhibition rate: 54.28%) with higher Notch1 and HES1 expression." (PMID 24894297, 2014). "Although, it was recently reported that DLL1, Notch1, Notch2, and HES1 are expressed in osteosarcoma cell lines, whether expression of Notch signalling molecules in osteosarcoma patient specimens is aberrant has not been clarified." (PMID 19455146, 2009). "The analysis of HES1 actions in primary canine osteosarcoma samples revealed that HES1 mRNA expression could be higher in tumor samples than in healthy bone tissue within individuals, while it was comparable to normal bone samples in dogs with faster tumor recurrence after treatment." (PMID 40563676, 2025). "A cohort study of 12 patients with osteosarcoma revealed that the NOTCH1 signaling pathway was significantly upregulated in tumor tissues, and the high expression of the NOTCH1 intercellular domain (NICD1) and the NOTCH target gene Hes1 was associated with a poor response to chemotherapy." (PMID 36975516, 2023). "However, in some tumors, Hes1 is upregulated during tumorigenesis, such as osteosarcomas." (PMID 21106062, 2010). "The role of other transcriptional regulators such as hairy and enhancer of split-1 (HES1) regulators in modulating CSC maintenance and chemoresistance in osteosarcoma is still unclear." (PMID 40563676, 2025). "For instance, at non-toxic doses, doxorubicin seems to inhibit the proliferation of osteosarcoma cells via the up-regulation of target genes such as HEY1, NOTCH1, HES1, and HES5." (PMID 37176108, 2023). "Exosomes from human umbilical vein endothelial cells promoted the self-renewal of CSCs in osteosarcoma by enhancing the expression of NOTCH1, Hes1, and Hey1 while blocking NOTCH signaling reversed the positive effect on the CSCs." (PMID 36975516, 2023). "Expression of HEY1, HES1, and BCL11B was also increased in human mesenchymal chondrosarcoma compared with other sarcomas such as myxoid liposarcoma, Ewing sarcoma, osteosarcoma, and synovial sarcoma." (PMID 37212282, 2023). "We believe that LSAMP is a tumor suppressor gene in osteosarcomas and that LSAMP suppress tumors by reducing the proliferation rate of cancer cells, possibly through upregulation of one or more of the genes HES1, CTAG2 and KLF10." (PMID 24885297, 2014). "Another study also found that HEY1 and other downstream target genes of Notch signaling including HES1, NOTCH1 and NOTCH2, were elevated in canine osteosarcoma by gene expression microarray analysis and reverse transcriptase - quantitative PCR (RT-qPCR)." (PMID 25023069, 2014). "The function of HES1 and KLF10 in bone biology also implies a function for these genes in osteosarcoma development." (PMID 24885297, 2014).
osteosarcoma (continued). "A study found that the osteosarcoma LM-7 cell line, which showed highly invasive and metastatic features, markedly upregulated the expression of NOTCH1, NOTCH2, Dll1, and Hes1 compared with normal human osteoblasts and the Saos-2 cell line with low metastatic potential." (PMID 36975516, 2023). "Similarly, the expressions of NOTCH target genes (Hes1, Hes5, and Hey1, among others) in U2OS and 143B osteosarcoma cells treated with sublethal doses of cisplatin were significantly higher than those of cisplatin-sensitive cells." (PMID 36975516, 2023). "The percentage of Hes1+ cells in the osteosarcoma specimens ranged from 2.3% to 28.5%, whereas there was only 0.55% Hes1 expression in the non-tumor counterparts, mainly in multinucleated cells." (PMID 27102300, 2016). "We performed IHC staining for Hes1 on 15 human osteosarcoma tissue samples and their non-tumor counterparts." (PMID 27102300, 2016). "Furthermore, NOTCH2 signal activation can promote the proliferation of osteosarcoma cells by upregulating NICD2 and Hes1, while blocking NOTCH2 can inhibit the proliferation of osteosarcoma cells by restraining the progression of the G0/G1 phase of the cell cycle." (PMID 36975516, 2023). "We have previously shown that the osteosarcoma cell line K7M2 actively expresses Notch genes (Notch1, Notch2, and Notch4; Hes1), but not Notch3." (PMID 27378829, 2016).
glioblastoma (21 papers, 2012 to 2026). The most malignant astrocytic tumor (WHO grade IV). "A separate study showed that Gli1, another Hh effector, was silenced by Hes1, a Notch-specific protein that encodes a basic helix–loop–helix (bHLH) transcriptional repressor, in glioblastoma neurosphere lines and primary human glioblastoma lines." (PMID 39766864, 2024). "For glioblastoma, POFUT1 knockdown reduces tumor volume and weight linked to decreased Notch activation (lower NICD, HES1, and HEY1 levels)." (PMID 40773107, 2025). "In cancer biology, midkine has been implicated in tumor progression in glioblastoma and neuroblastoma through ALK/NF-κB and Notch2/Hes1 signaling pathways." (PMID 41339619, 2025). "We further validated the regulation role of METTL3 in DLL3, NOTCH3, and HES1 and identify its influence in cell proliferation of glioblastoma cell lines via cell experiments." (PMID 34589481, 2021). "Interestingly, oscillatory expression of SOX2 has been observed in quiescent glioblastoma cells, reminiscent of HES1 oscillations in quiescent NSCs." (PMID 41142923, 2025). "Polo like kinase 2 (PLK2), a member of the serine/threonine kinases family, could induce glioblastoma resistance to temozolomide by regulating Hes family BHLH transcription factor 1 (HES1) and notch signaling." (PMID 37700319, 2023). "Intriguingly, the impairment of Notch signaling in secondary Glioblastoma, in which Hes1 expression is almost absent, is associated with the overexpression of ASCL1." (PMID 30832246, 2019). "The negative regulation of RND3 on HES1 was also detected in U87 glioblastoma cells." (PMID 26108681, 2015). "Furthermore, inhibition of Hes1 also had been reported to enhance apoptosis of U-87 MG glioblastoma cells." (PMID 25763821, 2015). "In order to determine whether EFEMP1 overexpression resulted in the activation of the Notch signaling pathway in the TMZ-resistant glioblastoma cells, we first assessed the expression of the Notch-induced genes HES1 and HEY1 by qRT-PCR." (PMID 24495907, 2014). "Subsequently, we determined whether blocking of the Notch pathway could overcome the EFEMP1-mediated resistance to TMZ, by treating the Hs683-WT and Hs683-Rl glioblastoma cells that demonstrated high expression of HES1/HEY1 with TMZ and the γ-secretase inhibitor (GSI) DAPT." (PMID 24495907, 2014). "Knockdown studies in colorectal, glioblastoma, and gastric cancer models have shown that reducing POFUT1 expression significantly decreases cleaved NICD levels, leading to lower expressions of HES1 and HEY1 and reduced tumor cell proliferation and invasion." (PMID 40773107, 2025). "HES1, a downstream target of Notch signalling, modulates SHH signalling in glioblastoma by binding to N-boxes within GLI1's first intron, suppressing its expression and potentially inhibiting the HH cascade." (PMID 39568072, 2024). "Moreover, combined treatment with DAPT represses HES1 and HEY1 expression, as well as LIF and YKL-40 levels, two new key players in Glioblastoma pathogenesis." (PMID 30832246, 2019). "Transcription factors like ASCL1, HES1, OLIG2, SOX2, and NOTCH-ligands (DLL1/3) play crucial roles in GBM plasticity by maintaining a pool of quiescent glioblastoma stem cells (GSCs)." (PMID 40358199, 2025). "Given that HES1 oscillations are known to facilitate the transition out of quiescence, it is plausible to hypothesise that sustained, non-oscillatory SOX2 expression could prevent quiescent glioblastoma cells from reactivating, thereby impairing tumour reactivation and progression." (PMID 41142923, 2025).